MTR (5-methyltetrahydrofolate-homocysteine methyltransferase)
Description:
Catalyzes the transfer of a methyl group from methylcob(III)alamin (MeCbl) to homocysteine, yielding enzyme-bound cob(I)alamin and methionine in the cytosol. MeCbl is an active form of cobalamin (vitamin B12) used as a cofactor for methionine biosynthesis. Cob(I)alamin form is regenerated to MeCbl by a transfer of a methyl group from 5-methyltetrahydrofolate. The processing of cobalamin in the cytosol occurs in a multiprotein complex composed of at least MMACHC, MMADHC, MTRR (methionine synthase reductase) and MTR which may contribute to shuttle safely and efficiently cobalamin towards MTR in order to produce methionine.
Synonyms: MS; cblG; HMAG
Tractability: Small molecule: a structure with a bound ligand is known; a high-quality ligand is known; it has a binding pocket of medium quality. PROTAC: ubiquitination databases record sites on it; its protein half-life has been measured; a small molecule that binds it is known.
Target class: Enzyme; Transferase
Safety:
Unwanted effects reported when the protein is acted on. In parentheses: how it was acted on, where the effect was seen, and who reports it.
drug toxicity (source: ClinPGx)
granulocytopenia (source: ClinPGx)
response to treatment with cisplatin or carboplatin (source: ClinPGx)
Gene: Protein-coding gene on chromosome 1 (236,795,260 to 236,921,278, forward strand). Ensembl gene ENSG00000116984.
Subcellular location: Cytoplasm
Subcellular location (Human Protein Atlas): Microtubules; Primary cilium; Basal body; Cytokinetic bridge; Cytosol
Pathways (Reactome):
Metabolism: Cobalamin (Cbl) metabolism; Methylation; Sulfur amino acid metabolism
Disease: Defective MTR causes HMAG; Defective MTRR causes HMAE
Signal Transduction: RHOH GTPase cycle
Gene Ontology:
Molecular function: methionine synthase activity; protein binding; cobalamin binding; metal ion binding; zinc ion binding
Biological process: cobalamin metabolic process; L-methionine biosynthetic process; axon regeneration; cellular response to nitric oxide; homocysteine metabolic process; methylation; nervous system development; response to axon injury; sulfur amino acid metabolic process; tetrahydrofolate metabolic process; L-methionine salvage; pteridine-containing compound metabolic process
Cellular component: cytosol; cytoplasm
Genetic constraint (gnomAD): Loss-of-function variants: 74 observed, 143.67 expected, observed/expected ratio (o/e) 0.52, 90% interval 0.43 to 0.62. The upper end of that interval is the gene's LOEUF score, 0.62, which puts it in group 2 of 6, group 1 being the genes least tolerant of losing a copy. Missense variants: 1,195 observed, 1,552.4 expected, observed/expected ratio (o/e) 0.77, 90% interval 0.73 to 0.81. Synonymous variants: 534 observed, 548.84 expected, observed/expected ratio (o/e) 0.97, 90% interval 0.91 to 1.04.
Gene-disease validity (ClinGen):
ClinGen rates the evidence that MTR causes each of these diseases.
methylcobalamin deficiency type cblG (autosomal recessive): Definitive.
Homologues: Orthologues: chimpanzee MTR (99% identical), macaque MTR (97% identical), guinea pig MTR (92% identical), rat Mtr (92% identical), mouse Mtr (91% identical), dog MTR (91% identical), rabbit MTR (90% identical), pig MTR (82% identical), tropical clawed frog mtr (81% identical), zebrafish mtr (73% identical), Caenorhabditis elegans metr-1 (63% identical). Paralogues in human: MTHFR (9% identical), BHMT (9% identical), BHMT2 (8% identical), UROD (6% identical).
Diseases named in the same sentence as MTR in open-access papers:
MTR is named in the same sentence as 127 diseases in open-access papers, as found by Europe PMC text mining. Sharing a sentence is not in itself a finding about the gene and the disease. The quoted sentences say what the papers report.
vitamin B12 deficiency (35 papers, 2009 to 2025). A disease characterized by low serum levels of vitamin B12, either inherited or acquired. "A vitamin B12 deficiency inhibits MTR function and causes 5-MTHF to accumulate since this process depends on vitamin B12 as a coenzyme." (PMID 40809450, 2025). "In situations of vitamin B12 deficiency, MTR activity is compromised, leading to an accumulation of 5-m-THF, as the enzyme is unable to utilize it as a methyl donor, leading to the methyl trap." (PMID 37960352, 2023). "Studies of carcinogenesis showed that an impaired MTR reaction, as observed in vitamin B12 deficiency or in cases of chronic ethanol ingestion, results in the continuous conversion of 5,10-methylene-THF to 5-methyl-THF." (PMID 21385350, 2011). "Additionally, vitamin B12 deficiency and the subsequent impairment of MTR activity leads to an accumulation of homocysteine, as it cannot be converted to methionine." (PMID 37960352, 2023). "Furthermore, vitamin B12 deficiency and impaired MTR activity lead to homocysteine accumulation, and elevated levels may increase the risk of cardiovascular disease, neurological illness, and other negative health outcomes." (PMID 40809450, 2025). "Genetic polymorphisms of MTHFR, MTR, MTRR, MMAA (methylmalonic aciduria (cobalamin deficiency) cb1A type), MMACHC (methylmalonic aciduria and homocystinuria, cblC type), and MUT have been analyzed." (PMID 32564308, 2020). "In the group with vitamin B12 deficiency in the presence of excess folic acid levels (condition for “methyl trap”), there was a reduction of MTHFR and MTR mRNA levels but increase in levels of MAT2a, PEMT, and CBS mRNA levels." (PMID 25003120, 2014). "This latter hypothesis proposes that vitamin B12 deficiency impairs overall folate metabolism because the generation of 5-CH3-THF is irreversible and that impairment of MTR prevents conversion of this compound to THF resulting in significant accumulation of 5-CH3-THF and depletion of THF." (PMID 26276101, 2015).
hyperhomocysteinemia (24 papers, 2006 to 2025). A serious metabolic condition caused by mutations in the MTHFR gene, medications, or nutritional deficiency. "The Mtrrgt allele is a knock-down mutation that leads to the disruption of one‐carbon metabolism in liver including a 62% reduction in MTR activity associated with plasma hyperhomocysteinemia and tissue-specific alterations in DNA methylation." (PMID 32257815, 2020). "The association of hyperhomocysteinemia with NTD risk implicates enzymes such as MTR, BHMT, and CBS that degrade homocysteine." (PMID 17035141, 2006). "Hyperhomocysteinemia (HHcy) is a metabolic disorder caused by improper removal and/or accumulation of Hcy most commonly arising from low dietary intake of folate or vitamin B12, or decreases in 5-methyltetrahydrofolate homocysteine methyltransferase (Mtr) and cystathionine β-synthase (Cbs) genes." (PMID 39919369, 2025). "Mutations in the MTR gene, which encodes MS, could also lead to hyperhomocysteinemia." (PMID 27047940, 2016). "Decreased SAM levels and hyperhomocysteinemia further indicates dysregulation of MTR with the hyperandrogenic phenotype of PCOS." (PMID 29232372, 2017). "In contrast with other diseases related to folate metabolism, the MTR variant has not been associated with hyperhomocysteinemia, an increased risk of neural tube defects, or vascular diseases." (PMID 28587068, 2017). "Therefore, a defect in MTR would lead to hyperhomocysteinemia, and low levels of Met and THF." (PMID 29232372, 2017).
breast carcinoma (10 papers, 2009 to 2025). "This study aimed to examine the joint effects of folate intake, polymorphisms of 5,10- methylenetetrahydrofolate reductase (MTHFR), methionine synthesis reductase (MTRR) and methionine synthase (MTR) genes and breast cancer risk." (PMID 27404801, 2016). "Statistically significant positive associations between folate intake and breast cancer risk were observed among women with the MTHFR 1298AA (P for trend = 0.003), 677CT and TT (P for trend = 0.011), and MTR 2756AA genotypes (P for trend = 0.049)." (PMID 19389261, 2009). "Variation in folate-pathway genes such as MTHFR, MTR and MTRR may disrupt homeostasis and confer significant risk of breast cancer, attributable to impaired DNA repair." (PMID 28241424, 2017). "A number of studies have examined MTHFR and MTR polymorphisms and found that variant genotypes of MTHFRrs1801133 GA + AA10, MTHFRrs1801131GG11 and MTRrs1805087 GA2 were associated with a decreased risk of breast cancer." (PMID 27404801, 2016). "Also, some meta-analysis studies found that SNPs in genes MDR, MTR, SLC4A7, ATR and CHEK1 were significantly associated with breast cancer susceptibility." (PMID 24386390, 2013). "Several studies have determined that dietary intake of B vitamins may be associated with breast cancer risk as a result of interactions between 5,10-methylenetetrahydrofolate reductase (MTHFR) and methionine synthase (MTR) in the one-carbon metabolism pathway." (PMID 19389261, 2009). "A number of studies have examined MTHFR and MTR polymorphisms and found that variant genotypes of MTHFR C677T are associated with an increased or decreased risk of breast cancer, while those of MTHFR A1298C are associated with a decreased risk and those of MTR A2756G with a decreased risk." (PMID 19389261, 2009).
folate deficiency (10 papers, 2011 to 2025). A nutritional condition produced by a deficiency of FOLIC ACID in the diet. "This study showed that MTHFR 677TT, MTHFR 1298AA, and MTR 2756AG + GG are independently correlated with a high risk of folate deficiency." (PMID 26266420, 2015). "In the present study, the MTHFR C677T and MTR A2756G polymorphisms each independently reduced the serum folate level and increased the folate deficiency risk." (PMID 26266420, 2015). "In this study, we found that the MTR 2756AG + GG genotypes resulted in not only a decreased serum folate level (p = 0.006) but also an increased folate deficiency risk compared with the wild-type genotype (p = 0.030)." (PMID 26266420, 2015). "Common polymorphisms of MTHFR (C677T and A1298C), MTRR (A66G) and MTR (A2756G) enzymes may influence the serum folate level and contribute to folate deficiency." (PMID 36554014, 2022). "Additionally, the patients with the MTR 2756AG + GG genotypes had a higher risk of folate deficiency than the 2756AA carriers (OR = 1.80, 95% CI 1.06–3.05, p = 0.030)." (PMID 26266420, 2015). "The MTR 2756A allele may prevent functional folate deficiency via MTR activity." (PMID 21385350, 2011). "The most sensitive pathways to folate deficiency are the MTCH and MTD activities of MTHFD1, MTHFR, MTR, DNMT, DHFR, and TYMS (row showing absolute flux differences between folate levels)." (PMID 28400561, 2017). "We aimed to explore the joint effect of the methylenetetrahydrofolate reductase (MTHFR) C677T and A1298C, methionine synthase (MTR) A2756G, and methionine synthase reductase (MTRR) A66G polymorphisms on folate deficiency in a Chinese hypertensive population." (PMID 26266420, 2015). "Furthermore, we have demonstrated that not only pairwise gene-gene interactions but also higher-order interactions of these gene polymorphisms (MTHFR C677T, MTHFR A1298C, MTR A2756G, and MTRR A66G) more strongly influence the incidence of folate deficiency." (PMID 26266420, 2015).
homocystinuria (10 papers, 2015 to 2025). An autosomal recessive inherited metabolic disorder caused by mutations in the CBS, MTHFR, MTR, and MTRR genes. "In summary, we have stabilized and been able to purify recombinant full-length human MTR and the clinical P1173L variant, which is the most common one found in MTR-deficient homocystinuria patients." (PMID 40513947, 2025). "The P1173L missense mutation is the most common clinical variant of MTR and causes homocystinuria, an inborn error of metabolism that is associated with aggressive occlusive cardiovascular diseases." (PMID 40513947, 2025). "Mutations in the MTR gene are associated with megaloblastic anemia, hypomethionemia, and homocystinuria; the last is characterized by increased blood homocysteine levels and attendant aggressive, occlusive cardiovascular diseases." (PMID 40513947, 2025). "Conversely, homocystinuria due to either MTHFR or MTR deficiency result in significantly lower levels of methionine compared to normal subjects." (PMID 26276101, 2015). "Mutations in MMAA, MMAB, and MUT (corresponding to cblA, cblB, and mut complementation groups) are associated with isolated methylmalonic aciduria, while mutations in MTRR and MTR (corresponding to cblE and cblG complementation groups) are associated with isolated homocystinuria." (PMID 38203763, 2024).
prostate carcinoma (7 papers, 2011 to 2024). A carcinoma that arises from epithelial cells of the prostate gland. "The enzymes involved in the one-carbon metabolism have been evaluated in a prostate cancer population through genomic sequencing defining at least two methionine synthase gene (MTR) polymorphisms (rs2837281 T>G and rs1131450 G>A) associated to a poorer prognosis in the Han Chinese population." (PMID 35201488, 2021). "Stratified analyses of the MTR gene rs1805087 A2756G polymorphism on prostate cancer risk." (PMID 30064122, 2018).
congenital heart disease (6 papers, 2019 to 2024). A heart disease that is present at birth. "Variants in the MTR and MTRR genes associated with congenital heart disease in humans." (PMID 39062651, 2024). "The association between methionine synthase (MTR) A2756G (rs1805087) polymorphism and the susceptibility to congenital heart disease (CHD) has not been fully determined." (PMID 35802641, 2022).
depression (4 papers, 2016 to 2023). "Common variants in MTR, PPARA, ABCC3, CALML5, CACNB2 and PCDHB10 genes were associated with deficits in neurocognitive tests performance, whereas a variant in SLCO1B1 and EPHA5 genes was associated with anxiety and depression." (PMID 31181069, 2019). "Functionally predicted germline common variants in MTR, PPARA, SLCO1B1, ABCC3, CALML5, CACNB2 and PCDHB10 genes were found to be significantly associated with deficits in neurocognitive tests performance, whereas a variant in EPHA5 gene was significantly associated with both anxiety and depression." (PMID 31181069, 2019). "Interestingly, BDNF emerged among the genes shared by depression and atherothrombosis, and it was well-connected to all the genes identified in both databases, namely, IL-1β, IL-6, IL-18, TNF, APOE, ACE, MTR, MTHFR genes." (PMID 35911513, 2022).
gastric cancer (4 papers, 2014 to 2022). A primary or metastatic malignant neoplasm involving the stomach. "In addition, our study suggested potential OR variations across strata of alcohol consumption, including associations of MTRR rs1801394 with esophageal and stomach cancer, and MTR rs1805087 with liver cancer." (PMID 25337902, 2014). "Low, or the absence, of correlation between EGFR dependency and expression is shown for CBS and SRM genes in rhabdoid cancer, for the MTR gene in gastric cancer and for the SRM gene in rhabdoid and neuroblastoma cancer cells." (PMID 36361596, 2022). "In addition, we detected potential heterogeneity across alcohol drinking status for ORs relating MTRR rs1801394 to esophageal (posterior homogeneity P = 0.005) and stomach cancer (posterior homogeneity P = 0.004), and ORs relating MTR rs1805087 to liver cancer (posterior homogeneity P = 0.021)." (PMID 25337902, 2014).
Hypertension (4 papers, 2012 to 2024). The presence of chronic increased pressure in the systemic arterial system. "The MTR 2756 A/G polymorphism is also associated with the risk of hypertension." (PMID 35284002, 2022). "We aim to investigate the effects of homocysteine metabolism enzyme polymorphisms (MTHTR C677T, MTHFR A1298C, MTR A2756G and MTRR A66G) and their interactions with folate, homocysteine on serum lipid levels in Chinese patients with hypertension." (PMID 26337056, 2015).
ischemic stroke (4 papers, 2013 to 2026). A stroke disorder caused by obstruction of blood flow to the brain, due to thrombotic (local blood clot formation) or embolic (due to a blood clot or other material traveling from another site) event. "Experimental and clinical data suggest that cytokine dysregulation and polymorphisms of thrombophilia-related genes (MTHFR, MTR, and MTRR) may jointly promote hypercoagulation, endothelial dysfunction, and thromboinflammation, thereby contributing to post-COVID ischemic stroke." (PMID 41898515, 2026).
Methylmalonic aciduria (4 papers, 2019 to 2024). Increased concentration of methylmalonic acid in the urine. "Released Cbl is exported from the lysosomes via the Lysosome Membrane Chaperone 1 (LMBD1) where it binds to methylmalonic aciduria type C and homocystinuria (MMACHC) proteins and then shuttled to cytoplasmic methionine synthase (MTR) and mitochondrial MUT." (PMID 35931118, 2022).